TSHR (thyroid stimulating hormone receptor)
Diseases named in the same sentence as TSHR in open-access papers (continued):
Sharing a sentence is not in itself a finding about the gene and the disease.
osteoporosis (13 papers, 2013 to 2025). A condition of reduced bone mass, with decreased cortical thickness and a decrease in the number and size of the trabeculae of cancellous bone (but normal chemical composition), resulting in increased fracture incidence. "Our results reveal a significant association between osteoporosis and a specific homozygous genotype combination (TSHR rs1991517 CC, FSHR rs6166 AA, and ADRB2 rs1042713 AA)." (PMID 41303600, 2025). "TSHR knockout causes osteoporosis and focal osteosclerosis in mice." (PMID 32508750, 2020). "The osteoporosis due to TSHR deficiency in the TSHR/KO mouse is of the high-turnover variety." (PMID 29042858, 2017). "Discussion of the current clinical strategies of TSHR based therapy for osteoporosis should first of all call for the understanding of a direct role of TSHR in bone remodeling." (PMID 41393297, 2025). "In conclusion, the translational premise is that pharmacological modulation of the TSHR pathway in bone cells can re-establish control over bone remodeling, offering a novel therapeutic strategy for osteoporosis, particularly high-turnover osteoporosis." (PMID 41393297, 2025). "Specifically, we identified osteoporosis-associated SNPs in GPCR genes, which were linked to impaired osteogenic differentiation in vitro including ADRB2 as well as CNR2, MTNR1B, FSHR, TSHR, LGR4, CALCR and WLS." (PMID 41393297, 2025). "Missense mutations in ADRB2, CNR2, FSHR, TSHR, CALCR, and GIPR genes were earlier associated with decreased BMD and osteoporosis in postmenopausal women as leading to amino acid substitutions and the possible receptor structure and/or function change." (PMID 39769358, 2024). "We found specific osteoporosis-linked SNPs in genes encoding key receptors involved in bone metabolism that are classified into rhodopsin (ADRB2, CNR2, MTNR1B, FSHR, TSHR, LGR4), secretin (CALCR, GIPR), and other T7M (WLS) receptor families." (PMID 39769358, 2024). "In recent years, due to the increasing incidence of secretory osteoporosis, bone loss, osteoporosis and their relationship with thyroid-stimulating hormone (TSH) and thyroid-stimulating hormone receptor (TSHR) have attracted increasing attention." (PMID 33726721, 2021). "There is strong evidence that the TSHR gene can regulate bone morphogenesis and bone density, and TSHR knockout mice display high-turnover osteoporosis." (PMID 31379930, 2019). "In animal studies, mice which lack the TSHR exhibited osteoporosis because of enhanced osteoclast formation." (PMID 29042858, 2017). "These authors found that osteoporosis in TSHR knockout mice was the result of an enhancement in osteoclast differentiation." (PMID 23818914, 2013). "A blocking antibody to TNFα abrogated this increased osteoclastogenesis, suggesting that osteoporosis in the TSHR−/− mice was TNFα mediated." (PMID 23818914, 2013). "To expand the data on the selected SNP combination, we have analyzed genomic DNA from 120 patients diagnosed with osteoporosis for the presence of selected SNPs in the FSHR (rs6166), TSHR (rs1991517), and ADRB2 (rs1042713) genes using allele-specific real-time PCR." (PMID 41303600, 2025). "In the absence of TSHR, osteoclast precursors showed enhanced RANKL-mediated differentiation and increased NF-κB activation, suggesting that osteoporosis in TSHR-/- mice results from an imbalance between bone resorption and formation, with increased osteoclast activity." (PMID 41393297, 2025). "Based on these findings, the development of TSHR agonists biased towards the ashutin-ashutin-1 and Gq/11-ERk1/2 pathways may contribute to the treatment of osteoporosis." (PMID 33726721, 2021). "Since TSHR may signal via β-arrestin 1 in humans in a clinically relevant manner, our data suggest that a TSHR positive allosteric modulator may have a potential role as a therapy for osteoporosis." (PMID 32508750, 2020).
osteoporosis (continued). "Recently, our study of postmenopausal women diagnosed with osteoporosis revealed a novel combination of three SNPs in GPCR genes — FSHR (rs6166), TSHR (rs1991517), and ADRB2 (rs1042713) — with a high frequency of approximately 20%." (PMID 41393297, 2025). "Although missense mutations in FSHR, TSHR, and ADRB2 have previously been associated with reduced BMD and osteoporosis, the combined effect of these specific SNPs has not yet been considered as a potential prognostic marker." (PMID 41393297, 2025). "For example, the extent to which native TSH and TSHβv work synergistically or antagonistically in delivering TSHR-mediated signals may provide important information into the specific role of TSHβ in AIT and osteoporosis." (PMID 33828532, 2021).
thyroid hypoplasia (12 papers, 2010 to 2025). Thyroid hypoplasia is a form of thyroid dysgenesis characterized by incomplete development of the thyroid gland that results in primary congenital hypothyroidism, a permanent thyroid deficiency that is present from birth. "Previous studies demonstrated that inactivating TSHR mutations results in mild or severe thyroid hypoplasia, and the heterogeneity was presumably due to different residual functions of TSHR mutations." (PMID 32565793, 2020). "Complete TSH resistance due to biallelic LOF TSHR mutations must be suspected in all patients with severe non-syndromic CH and severe thyroid hypoplasia diagnosed at birth by neonatal screening." (PMID 23154162, 2013). "Monogenic mutations causing dyshormonogenesis may underlie GIS CH; additionally, a small proportion of thyroid hypoplasia has a monogenic cause, such as TSHR and PAX8 defects." (PMID 32765423, 2020). "Isolated thyroid hypoplasia may occur because of PAX8 or TSHR mutations, and mutations in the transcription factors NKX2-1 and FOXE1 cause CH in association with more extensive developmental syndromes." (PMID 32765423, 2020). "A comprehensive, phenotype-driven, Sanger sequencing approach was used to identify genetic mutations underlying CH, by sequentially screening known dyshormonogenesis-associated genes and TSHR in GIS cases and TSHR and PAX8 in cases with thyroid hypoplasia." (PMID 32765423, 2020). "In hyt/hyt mutant mice, thyroid hypoplasia is observed postnatally, whereas TSHR mutant zebrafish have a significant reduction in the number and size of functional follicles." (PMID 31179344, 2019). "We screened a hypothyroid child with thyroid hypoplasia for mutations in PAX8, TSHR, NKX2.1, NKX2.5 and FOXE1 genes." (PMID 25146893, 2014). "Mutations in TSHR, the G-protein–coupled receptor for thyroid-stimulating hormone (TSH) cause a spectrum of phenotypes ranging from severe thyroid hypoplasia to a normal-sized GIS, with the severity correlating with the number of mutated TSHR alleles and the degree of receptor functional impairment." (PMID 32765423, 2020). "Complete TSH resistance due to biallelic LOF TSHR mutations must be suspected in all patients with severe not syndromic CH and severe thyroid hypoplasia diagnosed at birth by neonatal screening." (PMID 23154162, 2013).
toxic multinodular goiter (10 papers, 2014 to 2025). "In previous studies, somatic mutations of TSHR gene have been reported in toxic adenomas and toxic multinodular goiters, with a frequency ranging from 8 to 82% of cases." (PMID 30319546, 2018).
adenoma (9 papers, 1997 to 2024). A neoplasm arising from the epithelium. "Targeted NGS of the ten adenomas revealed a high prevalence of gain-of-function mutations of the TSHR gene (40%)." (PMID 33383892, 2020). "In the follicular adenoma samples, we identified mutations in the TSHR gene in seven of the 59 samples (12%): six of which were macrofollicular adenomas from the microarray study and one was a macrofollicular adenoma from the RT-PCR study." (PMID 19893615, 2009). "Naturally occurring mutations at position 281 have been reported in patients with toxic adenomas and have been shown to trigger TSHR constitutive activity." (PMID 38194289, 2024). "Aberrant TSHR gene methylation has been defined as a new factor that differentiates malignancy from benign adenoma." (PMID 37560303, 2023). "None of the microfollicular adenomas showed TSHR and GNAS mutations in the four exons explored." (PMID 19893615, 2009).
exophthalmos (9 papers, 2017 to 2025). "CAS, proptosis and TSHR-Ab reduced remarkably after the last pulse of the 12-week ivMP protocol compared to the first pulse (p < 0.001, p = 0.04 and p = 0.001, respectively)." (PMID 35456161, 2022). "Thyroid hormone levels and thyroid-stimulating hormone receptor antibody (TRAb) levels were measured, and the degree of exophthalmos was measured in all patients." (PMID 30671256, 2018). "It is notable that patients with Graves’ exophthalmos and dermopathy usually have very high circulating levels of TSHR autoantibodies." (PMID 28620373, 2017). "Moreover, TSHR autoantibodies play a role in Graves’ exophthalmos and Graves’ dermopathy by interacting with the TSHR expressed on orbital fibroblasts and dermal fibroblasts." (PMID 28620373, 2017). "Moreover, significant reductions in CAS, proptosis and TSHR-Ab were achieved." (PMID 35456161, 2022). "After treatment with IV methylprednisolone, TAO patients showed increased BCVA and decreased TSHR Ab, the superiorhemi-sector RNFLT, IOP, and proptosis but no significant changes in RPC density." (PMID 39039451, 2024).
breast carcinoma (7 papers, 2013 to 2025). "The expression of TSHR is increased in breast cancer tissues compared to adjacent normal mammary tissues." (PMID 35160139, 2022). "This article reviews the role of the thyroid axis in breast cancer, with a focus on the circulating levels of TSH and T4 as well as on the expression and function of TRs and TSHR in breast cancer cells." (PMID 35160139, 2022). "At the same time, the expression of TSHR was found common in BC, especially with a higher prevalence in low-grade breast cancer." (PMID 36313770, 2022). "In summary, a promoting role of anti-TSHR antibodies on breast cancer has been shown, while the role of anti-Tg and anti-TPO is unclear." (PMID 28536577, 2017). "It should be stressed that TSHR expression is common in breast cancer, with higher prevalence in low-grade breast cancer." (PMID 23680448, 2013). "However, the functional significance of the increased expression of TSHR in breast cancer is unclear." (PMID 35160139, 2022). "Anti-TSHR antibody levels were higher in breast cancer patients than in women with benign tumors or healthy controls, but a pathogenic role of anti-TSHR antibodies in breast cancer is not expected because breast tissue does not express TSHR." (PMID 28536577, 2017). "The ligand for TSHRAb, i.e. TSHR, is also present in breast cancer tissue." (PMID 23680448, 2013). "Specifically, the effects, if any, of direct TSH signaling through TSHR expressed in breast cancer cells have not been confirmed." (PMID 35160139, 2022). "In contrast to that, anti-TSHR antibodies do not appear to have a positive effect in manifest breast cancer." (PMID 28536577, 2017).
Insulin resistance (7 papers, 2008 to 2026). Increased resistance towards insulin, that is, diminished effectiveness of insulin in reducing blood glucose levels. "Decreased fasting blood glucose is observed in TSHR knockout mice, which is ascribed to decreased hepatic glucose production, and TSHR-Asp727Glu polymorphism is associated with insulin resistance in nondiabetic older men." (PMID 31179344, 2019). "Both TSHR and IGF1R could activate PI3K/AKT pathway, regulating insulin resistance." (PMID 34524974, 2021).
melanoma (7 papers, 2009 to 2025). A malignant, usually aggressive tumor composed of atypical, neoplastic melanocytes. "In particular, Ellerhorst and colleagues detected the TSHR in all cutaneous melanocytic lesions, namely benign nevi, dysplastic nevi, and melanomas." (PMID 36077430, 2022). "TSH receptor (TSHR) expression, at both mRNA and protein level, has been documented in skin tissues and different skin cell types including cultured keratinocytes, dermal fibroblasts, epidermal melanocytes, and melanoma cells." (PMID 36077430, 2022). "Shortly thereafter, the same group found that melanocyte-originated lesions ranging from a benign nevus, dysplastic nevi, and melanoma all express functional TSHR, with an upregulated expression in premalignant and malignant lesions, implying a higher sensitivity to TSH." (PMID 35805166, 2022). "A previous study interestingly showed that melanoma cells also expressed TSHR." (PMID 19593429, 2009). "This strategy could be similarly used for melanoma given the expression of TSHR induced by suppressing the MAPK and PI3K/Akt pathways and the enhancement of expression of other iodide-metabolizing genes by TSH in melanoma cells demonstrated in the present study." (PMID 19593429, 2009). "Only five genes were found to be predictive of good outcome when highly expressed in melanoma: LYSMD2, PSPIP2, SNAP23, TSHR, and CCPG1." (PMID 36553569, 2022). "Since TSHR plays an important role in up-regulating the iodide-handling genes in thyroid cells and is expressed in melanoma cells upon suppression of the MAPK and PI3K/Akt pathways, we investigated whether TSH treatment could affect the expression of iodide-handling genes in melanoma cells." (PMID 19593429, 2009). "Interestingly, a recent study showed common expression of TSHR in melanoma cells, but no or little expression in benign skin lesions, raising the possibility that other thyroid iodide-handling genes might also be expressible in melanoma cells." (PMID 19593429, 2009).
dermopathy (6 papers, 2016 to 2025). "Dermopathy develops in the presence of high TSHR antibody levels and is, with a frequency of 15%, a less common extra-thyroidal manifestation of GD." (PMID 28536577, 2017). "Although fibroblast stimulated by thyroid‐stimulating hormone receptor (TSHR) antibody, cytokines and growth factors have been postulated as target of the autoimmune process in the dermopathy, the pathogenesis of PTM remains unclear." (PMID 34047397, 2021).
lymph node metastasis (6 papers, 2015 to 2023). "In our study, an increasing PB TSHR mRNA expression level was related to lymph node metastasis and capsular invasion, which was positively associated with the rate of lymph node metastasis." (PMID 29088773, 2017). "A high PB TSHR mRNA expression level could indicate capsular invasion, lymph node metastasis, and/or BRAFV600E mutations." (PMID 29088773, 2017). "Patients with lymph node metastases, lymphovascular invasion and multifocality had significantly higher methylation levels of TSHR (p = 0.010, p = 0.020 and p = 0.013, respectively)." (PMID 36013156, 2022). "TSHR methylation was found in 71% of malignant nodules and 46% of benign nodules, and TSHR methylation occurred in patients with lymph node metastasis." (PMID 34923978, 2021). "In PTC patients, the preoperative PB TSHR mRNA expression level was positively correlated with lymph node metastasis rates (r = 0.387; and P = 0.001)." (PMID 29088773, 2017). "In PTC group, all 9 cases showing lymph node metastasis had positive methylation status of TSHr." (PMID 26519197, 2015). "The results showed a negative correlation between TSHR expression and invasive features, including advanced T stage, lymph node metastasis, ETE, and higher pathologic stage." (PMID 38174330, 2023). "In contrast, our results showed that the level of TSHR promoter methylation in PTC patients with lymph node metastasis was significantly higher than in patients with no lymph node metastasis." (PMID 36013156, 2022). "Previous studies reported that the incidence of TSHR promoter methylation in patients with lymph node metastasis is significantly higher than that in PTC with no lymph node metastasis." (PMID 36013156, 2022).
ovarian carcinoma (6 papers, 2016 to 2025). A malignant neoplasm originating from the surface ovarian epithelium. "Nevertheless, the details of underlying mechanisms by which TSHR modulates oncogenesis or tumor growth of ovarian cancer, and new strategies designed accordingly to intervene these processes, still await further exploration." (PMID 32698392, 2020). "Overactivation of TSHR can promote the proliferation of ovarian cancer cells by modulating G protein-coupled signaling pathways and indirectly activating epithelial growth factor receptors." (PMID 40532044, 2025). "TSHR is expressed in both normal ovarian tissue and human epithelial ovarian cancer cells and functions through the TSH-TSHR pathway." (PMID 40532044, 2025). "Although the roles remain elusive, the presence of TSHR in a bundle of extra-thyroid tissues, including some malignant tumors, such as ovarian cancer and hepatocellular carcinoma (HCC), has been found by researchers." (PMID 32698392, 2020). "These lines of evidence partially uncover the growth-promoting role of TSH/TSHR and/or thyrostimulin/TSHR in ovary and ovarian cancer." (PMID 32698392, 2020). "As such, unless a specific liver or ovarian cancer delivering or targeting system can be developed, the TSHR-targeting strategy cannot be applied to extra-thyroid cancers." (PMID 32698392, 2020). "In the present study we first explored the effects of thyrostimulin-TSHR signaling on ovarian cancer cell proliferation and then elucidated the signal flows among various downstreams involved." (PMID 27273257, 2016). "Next we screened several ovarian cancer cell lines in order to establish an appropriate cell model for thyrostimulin-TSHR signaling in ovarian cancers." (PMID 27273257, 2016). "In this study, we first found that TSHR is expressed in both rat normal ovarian surface epithelium and human epithelial ovarian cancers (EOCs)." (PMID 27273257, 2016). "Additionally, expression of an endogenous and functional TSHR has been reported in human epithelial ovarian cancer (EOC) cells." (PMID 41373675, 2025). "Full functionality of TSHR in NIH:OVCR-3 ovarian cancer cells was also demonstrated." (PMID 32698392, 2020). "TSHR signaling promotes the proliferation of ovarian cancer." (PMID 32293263, 2020). "Taken together, our preliminary findings provide hints that should help further studies into the involvement of thyrostimulin-TSHR signaling in various ovarian cancer progression traits, such as the capabilities of cancer cells to undergo anti-apoptosis, invasion and/or metastasis." (PMID 27273257, 2016). "To link TSHR signaling with ovarian cancer progression, we first tested whether TSHR is expressed in OSE." (PMID 27273257, 2016). "Thus, this cell line was chosen as an appropriate cell candidate for exploring the effects of thyrostimulin-TSHR signaling on ovarian cancers." (PMID 27273257, 2016). "Thus, it is possible that thyrostimulin-TSHR signaling may function similarly to other gonadotropins in promoting ovarian cancer progression." (PMID 41373675, 2025). "However, recent evidence suggests that TSHR is highly expressed in ovarian cancer tumors." (PMID 28439256, 2017). "Therefore, TSHR activity appears to be correlated to ovarian cancer progression." (PMID 28439256, 2017). "Furthermore, we investigated eight cases of epithelial ovarian cancers (EOCs) using samples from the tumors and the corresponding normal tissues adjacent to the tumors; these were used to detect the protein level and transcript level of TSHR." (PMID 27273257, 2016). "Therefore, it would be interesting to investigate further whether and how thyrostimulin-TSHR signaling regulates the activities of these proteins in ovarian cancers." (PMID 27273257, 2016). "However, whether thyrostimulin-driven TSHR activation contributes to ovarian cancer progression in a similar way to gonadotropin receptors has never been explored." (PMID 27273257, 2016).